COMT (catechol-O-methyltransferase)
Diseases named in the same sentence as COMT in open-access papers (continued):
Sharing a sentence is not in itself a finding about the gene and the disease.
cancer (continued). "There are several theoretical reasons for the potential implications of the MAO/COMT enzyme in OPMD and cancers of the oral cavity and pharynx, particularly among BQ chewers." (PMID 34209963, 2021). "In this review, we discuss the risk of cancer associated with anti-diabetic therapies, including DPP-4 inhibitors and SGLT2 inhibitors, and the role of catechol-o-methyltransferase (COMT), AMPK, and cell-specific glucocorticoid receptors in cancer biology." (PMID 32498358, 2020). "The catechol-O-methyltransferase (COMT) enzyme, which forms reactive adducts with DNA, is considered to be a potentially important contributor to cancer development." (PMID 26786282, 2016). "COMT upregulation in PDAC and other cancer types compared with healthy tissues suggests that EAPB02303 could be preferentially bioactivated at tumor sites, potentially enhancing its efficacy and reducing its toxicity." (PMID 40490448, 2025). "The clinical significance of pharmacogenetic biomarkers OPRM1 rs1799971, COMT rs4680 and ABCB1 (rs1045642, rs1128503, and rs2032582) should be further explored in future studies to improve precision pain management amongst Asian patients with cancer pain." (PMID 36422103, 2022). "There is increasing evidence of potential genetic (APOE, COMT, BDNF), plasma (e.g., inflammatory molecules, circulating microRNAs, exosomes, short-chain fatty acids and others), cerebrospinal fluid and neuroimaging biomarkers of CRCI in cancer patients." (PMID 34970595, 2021). "Our findings support the hypothesis that genetic variations and downregulation of MAO and COMT may play a putative role in the development of OPMD and cancers of the oral cavity and pharynx in men." (PMID 34209963, 2021). "Our studies and those of others have shown that genetic factors play a key role in vulnerability to pain in cancer patients, and have identified important candidate genes such as opioid receptor genes (e.g., OPRK1 and OPRM1), catechol-O-methyltransferase (COMT), and cytokine genes." (PMID 26872611, 2016). "Under physiological conditions, COMT can metabolize EGCG to 4′′-o-methyl-EGCG (MeEGCG) and 4′,4′′-di-o-methyl-EGCG (DiMeEGCG), resulting in a reduction of the oral bioavailability of EGCG and reduced cancer-related biological activities of EGCG." (PMID 27483305, 2016). "To test this hypothesis, we evaluated a selected panel of SNPs in GSTP1, COMT, and TPMT with cancer outcome, ototoxicity, and peripheral neuropathy in an existing cohort of men with TGCT who have received at least one course of cisplatin-based chemotherapy." (PMID 23248619, 2012). "Exploration of whether these genes (HTR2A, COMT, PRODH) may influence immune cell differentiation through the immune pathways would provide interesting and plausible evidence for the correlation between SCZ and cancers." (PMID 37564635, 2023). "Also, considerable upregulation of COMT was observed in 21 cancers(GBM、GBMLGG、LGG、BRCA、LUAD、ESCA、STES、COAD、COADREAD、PRAD、STAD、HNSC、LUSC、SKCM、BLCA、THCA、READ、PAAD、ALL、LAML、CHOL) and significant downregulation in 8 cancers(KIPAN、KIRC、WT、OV、TGCT、UCS、PCPG、KICH)." (PMID 37564635, 2023). "COMT and HSD17B1 were identified to be responsible for the differential estrogen response between ES clusters A and B, and the estrogen response may be correlated with the differentiation and cancer stemness of CCA at the single-cell level." (PMID 35664769, 2022). "The methyl (CH3) group with which COMT carries out targeted destruction of catechol compounds is provided by S-adenosyl methionine (SAM), a key methyl donor in the folate metabolic pathway with a pivotal role in epigenetic alterations in general, and in epigenetic changes in cancer in particular." (PMID 24460628, 2014). "Herein, a preliminary conclusion could be reached that the effect of SCZ-related genes HTR2A, COMT, and PRODH was highly variable in different cancers, and the prognostic significance of SCZ on cancer development needed to be explicitly explored for various cancers." (PMID 37564635, 2023).
psychiatric disorder (72 papers, 2005 to 2025). A disorder characterized by behavioral and/or psychological abnormalities, often accompanied by physical symptoms. "COMT rs4680 polymorphism has often been associated with different phenotypes and psychopathy-related behaviors in mental disorders, related to alterations in catecholaminergic and especially dopaminergic signaling." (PMID 40305338, 2025). "The COMT Val108/158Met polymorphism has been widely associated with susceptibility to mental illness (e.g., Hosák, 2007)." (PMID 37637902, 2023). "The involvement of COMT in monoamine metabolic pathways indicates the pleiotropic effect of this gene on the susceptibility to psychiatric disorders and symptoms." (PMID 35888708, 2022). "In this review, we will address what current literature has discovered about the association of polymorphisms in COMT genotype with neurological and psychiatric disorders and the scope for the knowledge to be applied for advancement in therapeutics." (PMID 34725583, 2021). "Variants of COMT genotype have been extensively studied in association with various neurological and psychiatric disorders." (PMID 34725583, 2021). "We recommend future researchers conduct more randomized control trials (RCTs) to investigate the therapeutic role of COMT genotype polymorphism in neurological and psychiatric disorders." (PMID 34725583, 2021). "A recent meta-analysis comprehensively studied the association between COMT Val158Met genotype and psychiatric disorders." (PMID 34725583, 2021). "This review article aims to discuss what recent research has discovered about the association of COMT genotype polymorphism with neurological and psychiatric disorders and the scope for the knowledge to be applied for advancement in therapeutics." (PMID 34725583, 2021). "The association between COMT genotype polymorphism with neurological and psychiatric disorders has been actively researched in the last few decades." (PMID 34725583, 2021). "We searched PubMed and Google Scholar databases using the keywords ‘catechol-O-methyltransferase, ‘COMT’, ‘COMT genotype’, ‘polymorphism’, ‘neurological disorders’, ‘psychiatric disorders’, and ‘mental health disorders’ and found a total of 1656 articles." (PMID 34725583, 2021). "This review focused on the association of the various COMT genotype polymorphisms in neurological and psychiatric disorders, emphasizing its therapeutic implications, especially towards personalized medicine." (PMID 34725583, 2021). "Recently, the focus of research has shifted towards newer concepts involving COMT gene variants and neurological and psychiatric disorders to direct research towards improved treatment strategies." (PMID 34725583, 2021). "The interpretation of the influence of this COMT functional polymorphism in psychiatric disorders is therefore complicated by sex-, but also by ethnic-related differences in allele distributions." (PMID 30018555, 2018). "In TwinsUK, one CpG of IGF1 was associated with birth weight discordance while there was a 13% average difference in methylation of COMT (implicated in psychiatric disorders) between MZ twins at 5 years." (PMID 30096154, 2018). "A common SNP, Val158Met in exon 4 of the COMT gene, has been observed as being linked to various psychiatric disorders, one of which being suicide." (PMID 27721799, 2016). "In a number of studies, COMT has been associated with cognitive impairment in several psychiatric disorders, and also in the general population." (PMID 23861766, 2013). "Future studies including patients affected by psychiatric disorders are required to clarify the relationship between impulsivity and the COMT val158met polymorphism." (PMID 24039968, 2013). "For instance, polymorphisms in the catechol-O-methyltransferase enzyme have been implicated in human mental illness with the presence of certain SNPs resulting in increased susceptibility to posttraumatic stress disorder (PTSD)." (PMID 23878520, 2013).
psychiatric disorder (continued). "A meta-analysis by Taylor investigating the specific Val158Met polymorphism of COMT reported pleiotropic effect of the polymorphism across multiple psychiatric disorders, further highlighting COMT’s relevance in understanding predispositions for transdiagnostic mental health ailments." (PMID 41440133, 2025). "In this context, the most common functional polymorphism of COMT (named rs4680 (replacement of G472A) or Val105/158Met) has been associated with various cognitive phenotypes, changes in brain activation and structure, and psychiatric disorders." (PMID 35741850, 2022). "Out of the total number, 17 studies, including 8638 subjects, explored the association between COMT genotype polymorphism and neurological and psychiatric disorders, and nine studies were drug-based or pharmacogenetic studies that included a total of 5115 subjects." (PMID 34725583, 2021). "COMT polymorphism is one of the most common genes that have been studied in mental illness." (PMID 32618128, 2020). "Additionally, these findings contribute to the growing literature on sex-specific effects of COMT on the predisposition to psychiatric disorders and personality traits." (PMID 25722988, 2015). "Importantly, this COMT polymorphism predicted behaviors in healthy adults which tie to psychiatric disorders —thus, investigation of this genotype in healthy individuals has applications for clinical research." (PMID 22216231, 2011). "We hypothesized that COMT variation may confer a general risk for psychiatric disorders and have genotyped four COMT variants (Val158Met, rs737865, rs165599, and a SNP in the P2 promoter [-278A/G; rs2097603]) in 394 Caucasian cases and 467 controls." (PMID 16232322, 2005). "COMT, encoding the protein catechol-O-methyltransferase responsible for degrading catecholamines such as norepinephrine (particularly in the prefrontal cortex), is a gene in the 22q11.2 region and is often thought of as a risk gene candidate for psychiatric disorders." (PMID 37328766, 2023). "Regarding sex difference, we found that COMT, a gene linked to sex differences in brain function and predisposition to psychiatric disorders, was upregulated in U1M but downregulated in U2F hFOs post VPA exposure, suggesting that COMT may mediate the sex-differential effects of VPA exposure." (PMID 35351869, 2022). "There are accumulating and sometimes compelling data showing that COMT has marked sexually dimorphic effects on brain function and its dysfunction in psychiatric disorders." (PMID 37240556, 2023). "The enzyme catechol-O-methyltransferase (COMT) has been theorized to play a role in psychiatric disorders." (PMID 37031222, 2023). "The catechol-O-methyltransferase (COMT) is a candidate gene to provide promising evidence of psychiatric disorders, but there is a knowledge gap between the genetic factor and multiple physical activity-related injuries (PARIs)." (PMID 34682575, 2021). "The COMT enzyme plays a major role in the pathophysiology of various neurological and psychiatric disorders." (PMID 34725583, 2021). "Variations in the activity of COMT influence various human disorders from psychiatric diseases to estrogen-induced cancers." (PMID 28066248, 2016). "One of the more common genes studied in mental illness is the Val158Met substitution of the catechol-O-methyltransferase (COMT) gene." (PMID 27683563, 2016). "Our finding are consistent with other studies showing genetic associations between the COMT and DAOA genes and impaired cognition both in psychiatric disorders and in the general population." (PMID 23861766, 2013). "Gene and environmental interactions on psychiatric diseases have been widely accepted and our study suggests that there is an interaction between the COMT gene and childhood trauma in the development of heroin use." (PMID 23155402, 2012).
psychiatric disorder (continued). "There appears to be excessive transmission of the allele that produces more COMT activity and less PFC DA in some psychiatric disorders, which would cause less efficient PFC processing." (PMID 19228412, 2009). "We included subjects with a range of psychiatric diseases, and genotyped 4 SNPs including the Val/Met polymorphism, the P2 promoter SNP (-278A/G, rs2097603) as well as SNPs rs737865 and rs165599 to test the hypothesis that COMT genetic variation is associated with the risk for psychiatric illness." (PMID 16232322, 2005). "In sum, our findings support the previous notion that COMT gene–environment interactions could be related to suicidal ideation in various mental illnesses." (PMID 32618128, 2020). "Such an investigation of sex-dependent influences of COMT may shed light on the neurobiology of the sex differences present in many psychiatric disorders." (PMID 29270116, 2017). "Therefore, POMC and COMT are both potential pharmacological targets for treating psychiatric disorders." (PMID 27917343, 2016). "The COMT exonic variant (Val158Met) has been associated with various psychiatric disorders (for a review see: Hosak, 2007), but no positive findings were obtained here with heroin abuse either with single marker or with multilevel analysis." (PMID 23840506, 2013). "Moreover, COMT demonstrated sexual dimorphism in psychiatric disorders, and there are sex-related differences in cognitive performance and brain functions, probably due to the estrogen cycle as disruptive behavior problems and CD are significantly more common in males than females." (PMID 40305338, 2025). "Additionally, modulation of COMT activity by sex may contribute to sex differences in many psychiatric disorders." (PMID 29270116, 2017). "Several candidate genes (e.g: BDNF; FKBP5; SLC6A4; AVP; NR3C1; CRH; COMT; MAOA; OXTR and APOE) to psychiatric disorders have been quoted in epigenetic studies using locus-specific assays." (PMID 30218003, 2018). "To demonstrate the utility of BECon, we assessed key candidate genes often investigated for changes in DNAm in relation to psychiatric disorders (BDNF, COMT, OXTR and DRD4)." (PMID 28763057, 2017). "Although the current consensus is that the COMT Val158Met polymorphism does not play a dominant role in most mental health disorders, the pleiotropic influence of this gene on intermediate phenotypes of several psychiatric disorders has drawn considerable interest." (PMID 29270116, 2017). "The studies that have found associations have sometimes found associations in patient populations but not in controls and sometimes found associations of COMT genotype interacting with some other variable, whether it be psychiatric disorder, gender or complex age and gender interactions." (PMID 22479488, 2012). "Catechol-O-methyltransferase (COMT) is a key enzyme for dopamine catabolism and COMT is a candidate gene for human psychiatric disorders." (PMID 20618449, 2010). "The COMT and DAOA genes may contribute to the pathophysiology of psychiatric disorders, and especially cognitive manic symptoms, by the combined effect of dopaminergic and glutamatergic pathways." (PMID 23861766, 2013).
tumor (29 papers, 2013 to 2026). "COMT was considered a tumor suppressor that is associated with anticarcinogenesis, antiproliferation, pro-apoptosis, anti-angiogenesis, and anti-inflammation." (PMID 36147313, 2022). "Specifically, FN1 (Log2 FC = 6.2), UGT1A1 (Log2 FC = 6.1), AGT (Log2 FC = 3.31), and COMT (Log2 FC = 2.4) were significantly upregulated in tumor tissues compared to normal tissues." (PMID 40564071, 2025). "In contrast, tumors in pCMV mice were visible by week 1 and growth was markedly enhanced by week 3 as the average tumor volume grew to 457 mm3 in controls whereas in comparison, stable COMT cells grew to only 5.6 mm3 in mice (p<0.0049)." (PMID 34587154, 2021). "In concordance, COMT expression abrogated xenograft tumor formation and this inhibition continued throughout the experimental period of three weeks." (PMID 34587154, 2021). "A previous report also indicated that the overexpression of COMT significantly decreased tumor invasion." (PMID 34209963, 2021). "γ-Synuclein overexpression is known to cause an increase in proliferation, invasiveness and metastasis, and γ-synuclein, along with calreticulin and catechol-o-methyltransferase, is reported to be a tumor marker in BCa." (PMID 25915536, 2015). "A lack or low level of Phase II detoxifying enzymes, such as catechol-O-methyltransferase (COMT) and GSTs, might lead to quinones accumulation, resulting in DNA adducts formation and tumor initiation." (PMID 33513690, 2021). "A similar effect was observed in vivo as COMT-expressing cells inhibited xenograft tumor growth." (PMID 34587154, 2021). "Based on the previous literature and the overexpression of dopamine that is characteristic of NB, we hypothesized that inhibition of COMT by Tolcapone in NB cells would lead to tumor cell death." (PMID 28429453, 2017). "Therefore, COMT + MAO-A inhibition improved the separation of the healthy pancreas from the tumour." (PMID 23497589, 2013). "The study revealed that COMT was expressed at high levels in all cell lines of GBMLGG patients, HTR2A showed more overexpression in tumor cells, and PRODH exhibited more overexpression in T cells." (PMID 37564635, 2023). "Pretreatment with COMT + MAO-A inhibitors improved the differentiation of pancreas from the surrounding tissue and healthy pancreas from tumour." (PMID 23497589, 2013). "When mice received COMT + MAO-A inhibitors, the uptake was high in the healthy pancreas but low in the tumour-bearing pancreas." (PMID 23497589, 2013). "COMT + MAO-A inhibitors increased the 18F radioactivity uptake in pancreatic tissue, while the uptake in tumours is poor due to the formation of [18F]FDA as main metabolite." (PMID 23497589, 2013). "No mutations in catechol-O-methyltransferase (COMT), fatty acid binding protein 4 (FABP4), myoglobin (MB) and metallothionein 2A (MT2A) were detected in COAD tumor tissues." (PMID 36203457, 2022). "On the other hand, COMT was downregulated in NB (p < 0.0001) without significant impact, considering that MNs are massively produced in the tumor." (PMID 33456713, 2021). "Importantly, 2-methoxy estrogens (2-OMEs), generated by catechol-O-methyltransferase (COMT), are potent inhibitors of tumor cell proliferation and angiogenesis, and are thus protective." (PMID 29290988, 2017). "The genomic sequencing of tumor biopsies from patients with NB showing upregulation of COMT uncovered this potentially novel therapy not previously considered in the past." (PMID 28429453, 2017). "For [18F]FDOPA studies, tumour-bearing mice and sham-operated controls were pretreated with enzyme inhibitors of aromatic amino acid decarboxylase (AADC), catechol-O-methyl transferase (COMT), monoamine oxidase A (MAO-A) or a combination of COMT and MAO-A." (PMID 23497589, 2013). "However, the difference between the healthy pancreas and tumour was not clear in all cases after COMT + MAO-A administration, and the benefit over vehicle pretreatment remained modest." (PMID 23497589, 2013).